CFHR3 (complement factor H related 3)
Diseases named in the same sentence as CFHR3 in open-access papers (continued):
Sharing a sentence is not in itself a finding about the gene and the disease.
tumor (14 papers, 2021 to 2025). "Also, we found that the mRNA expression of C1R, C6, C7, and CFHR3 was associated with tumor grade, while the mRNA expression of C1R, C6, and CFHR3 was associated with the cancer stage." (PMID 34813686, 2022). "As such, presence of complement factor H-related 3 negatively correlated with tumor infiltrating lymphocytes like CD8 + T cells." (PMID 39034327, 2024). "A significant increase in UCK2, HMMR, and MAGEA6 expression and a significant decrease in CXCL8, EPO, PPARGC1A, FTCD, and CFHR3 expression was observed in tumor tissues." (PMID 38694506, 2024). "Even though the expression of HIF1α and CA9 was the same in these two groups, tumor tissues derived from mice injected with HepG2 cells overexpressing CFHR3 had lower PCNA expression levels." (PMID 35549979, 2022). "CFHR3 downregulation is closely associated with large (T3-T4) HCC, tumor recurrence, and advanced (stage III-IV) clinical stage, functioning as an independent factor for the prognoses of HCC patients." (PMID 35852862, 2022). "One supportive evidence is CFHR3, a similar variant of CFHR4 with overlapping functions, was reported highly expressed at the normal liver tissue, while the HCC tumor expressed CFHR3 in significantly lower level." (PMID 36338737, 2022). "Because a hypoxic microenvironment spontaneously occurs during tumor progression in vivo, we determined the effects of CFHR3 in vivo." (PMID 35549979, 2022). "BAIAP2L2, pituitary tumour-transforming gene 1 (PTTG1) and complement factor H-related 3 (CFHR3) have also been reported to be overexpressed in many types of human cancer and to promote tumour cell angiogenesis, migration and invasion." (PMID 36217206, 2022). "We further studied the relationship between mRNA expression levels of C1R, C6, C7, CFP, CFHR3, and tumor stages in HCC patients by using the UALCAN database since these genes were considered to have prognostic value." (PMID 34813686, 2022). "By performing the TIMER analysis, we established that there was a positive relationship between CFHR3 and the infiltration of B cells, neutrophils, and macrophages but negatively correlated with tumor purity, CD8+ T cells, and monocytes." (PMID 36213819, 2022). "Recent studies show that enhanced CFH or CFHR (CFHR1 and CFHR3) levels either by gene therapies or by CFH reconstitution might lower tumor burden in HCC." (PMID 34813686, 2022). "Also, C1R, C6, C7, and CFHR3 presented correlations with tumor grades and cancer stage in HCC patients, while CFP presented correlations with the immune markers of tumor immune cells in HCC." (PMID 34813686, 2022). "In addition, lower mRNA expression of C1R, C6, C7, and CFHR3 were found correlated with advanced cancer stages and higher tumor grades in HCC patients." (PMID 34813686, 2022). "As tumor grades increased, the mRNA expressions of C1R, C6, C7, and CFHR3 tended to be lower." (PMID 34813686, 2022). "Previous research has suggested CFHR3 as a novel prognostic biomarker for HCC, and its downregulation enhances tumor aggressiveness, correlating with higher T-stages, advanced clinical stages, and increased recurrence risk." (PMID 40918463, 2025). "Differential expression analysis of TCGA-LIHC tumor tissues and adjacent normal tissues revealed that the expression differences of TMEM45A, S100A10, SERPINA12, BHMT, CFHR3, RPL8, and STMN1 all exceed a 2-fold change." (PMID 39176099, 2024). "Chi-square test analysis showed that downregulation of CFHR3 was positively relevant to elevated level alpha-fetoprotein (AFP), high histological grade, large tumor, HCC recurrence as well as advanced TNM stage." (PMID 35852862, 2022). "The results showed that the mRNA expression levels of C1R, C6, C7, and CFHR3 were correlated with the tumor grade of HCC patients, while only CFP was not correlated with the tumor grade of HCC patients." (PMID 34813686, 2022).
tumor (continued). "The results showed that the expression levels of C1R, C6, and CFHR3 were correlated with the tumor stage of HCC patients, while the expression levels of C7 and CFP were not correlated with the tumor stage of HCC patients." (PMID 34813686, 2022).
cancer (6 papers, 2015 to 2022). A tumor composed of atypical neoplastic, often pleomorphic cells that invade other tissues. "Despite CFHR3 low expression was detected in some certain cancers, the underlying molecular mechanisms of low CFHR3 expression in cancers are still largely unknown." (PMID 35852862, 2022). "The expression of CFHR3 varies widely across 21 cancer types." (PMID 36213819, 2022).
infection (5 papers, 2013 to 2024). The state of being infected such as from the introduction of a foreign agent such as serum, vaccine, antigenic substance or organism. "The complement factors C3, C9, and CFHR3 (complement factor H-related protein 3 precursors) were down-regulated with the wt isolate, which could be related to an attempt of the virus to regulate the inflammatory response during infection." (PMID 35215144, 2022). "Thus, in vitro studies are a limitation to investigate the effect of FHR-3 on bacterial infections and future studies should focus on the use of P. aeruginosa Cfhr-3 knock-out mice model of infection to evaluate the role of this complement regulator factor in vivo." (PMID 39295874, 2024).
neurologic disorder (1 paper, 2011). "In EA, we found that tag SNP rs6677604 of CFHR3-1Δ was associated with the absence of neurologic disorder." (PMID 21637784, 2011).
CFHR3 also shares sentences with these, for which no sentence is quoted: hemolytic-uremic syndrome (4 papers); Hypertension (2); nephropathies (2); thrombotic thrombocytopenic purpura (2); autoimmune (1); autoimmune disease (1); bacterial infection (1); biliary tract cancer (1); Blood Pressure (1); cardiovascular disease (1); COVID-19 (1); degenerative diseases (1); fibromuscular dysplasia (1); gastric cancer (1); geographic atrophy (1); Holt-Oram syndrome (1); Hyporeflexia (1); idiopathic interstitial pneumonia (1); keratoconus (1); liver cancer (1); malaria (1); melanoma (1); membranoproliferative glomerulonephritis (1); muscular dystrophy (1); myeloma (1); paraplegia (1); retinopathy (1); spinal muscular atrophy (1); Thrombocytopenia (1); thrombotic microangiopathy (1).
A further 2 diseases each share a sentence with CFHR3 in 1 paper.